ANKS3 (ankyrin repeat and sterile alpha motif domain containing 3)
Description:
May be involved in vasopressin signaling in the kidney.
Synonyms: KIAA1977; FLJ32345; FLJ32767
Tractability: PROTAC: UniProt records ubiquitination sites on it; ubiquitination databases record sites on it.
Gene: Protein-coding gene on chromosome 16 (4,696,510 to 4,734,378, reverse strand). Ensembl gene ENSG00000168096.
Subcellular location: Cell projection, cilium; Cytoplasm
Subcellular location (Human Protein Atlas): Nucleoplasm; Cytosol
Gene Ontology:
Molecular function: protein binding
Cellular component: cilium; cytoplasm
Genetic constraint (gnomAD): Loss-of-function variants: 60 observed, 67.53 expected, observed/expected ratio (o/e) 0.89, 90% interval 0.72 to 1.1. The synonymous counts are far from expectation, so gnomAD's model fits this gene poorly and the ratio says little. Missense variants: 1,130 observed, 837.29 expected, observed/expected ratio (o/e) 1.35, 90% interval 1.28 to 1.42. Synonymous variants: 481 observed, 338.26 expected, observed/expected ratio (o/e) 1.42, 90% interval 1.32 to 1.53.
Homologues: Orthologues: chimpanzee ANKS3 (99% identical), macaque ANKS3 (95% identical), pig ANKS3 (86% identical), guinea pig ANKS3 (84% identical), dog ANKS3 (84% identical), mouse Anks3 (82% identical), rat Anks3 (81% identical), rabbit ANKS3 (62% identical), tropical clawed frog anks3 (58% identical), zebrafish anks3 (50% identical), Caenorhabditis elegans mlt-3 (18% identical).
Diseases named in the same sentence as ANKS3 in open-access papers:
ANKS3 is named in the same sentence as 7 diseases in open-access papers, as found by Europe PMC text mining. Sharing a sentence is not in itself a finding about the gene and the disease. The quoted sentences say what the papers report.
cyst (3 papers, 2015 to 2021). A sac-like closed membranous structure that may be empty or contain fluid or amorphous material. "Association of ANKS3with ciliary abnormalities, its interaction with nephronophthisis proteins (NPHP1, NPHP4, NPHP8) and its role in cyst formation have been demonstrated following ANKS3 knockdown in zebrafish." (PMID 26327442, 2015). "Interestingly, LKB1 (STK11) was shown to be part of a ciliary module comprising NPHP1, NEK7, ANKS3 and polycystin-1 that regulates cilia-controlled secretion of CCL2, a chemokine that promotes macrophage recruitment and consequent cyst growth and interstitial inflammation." (PMID 34055783, 2021).
Renal cyst (3 papers, 2014 to 2018). A fluid filled sac in the kidney. "The R823W mutation associated with cystic kidney disease causes a destabilization of the ANKS6 SAM domain which disrupts binding to ANKS3." (PMID 24998259, 2014). "Bicc1 and the ankyrin and SAM domain proteins ANKS3 and ANKS6 all suppress renal cysts and can coprecipitate each other." (PMID 29995892, 2018). "The emergence of a protein network involving ANKS6, ANKS3 and BICC1 provides important clues on novel mechanisms involved in the formation of renal cysts." (PMID 26327442, 2015).
nephronophthisis (2 papers, 2015 to 2018). Progressive tubulointerstitial injury, inherited in an autosomal recessive pattern, caused by mutations in genes involved in ciliary function, which may result in an end stage renal failure. "We report initial characterization of the molecular consequences of in vivo renal downregulated expression of mouse ANKS3, a structurally related protein partner of ANKS6 involved in renal cystogenesis in mice and rats and nephronophthisis in humans." (PMID 26327442, 2015). "Likewise, it is important to monitor whether knockdown of Anks3 interaction partners, such as INVS, results in similar metabolic phenotypes in order to improve the understanding of nephronophthisis on metabolic level." (PMID 29899363, 2018).
ANKS3 also shares sentences with these, for which no sentence is quoted: coronary artery disease (1 paper); diabetes (1); renal diseases (1); schizophrenia (1).